TNPO2 (transportin 2)
Description:
Probably functions in nuclear protein import as nuclear transport receptor. Serves as receptor for nuclear localization signals (NLS) in cargo substrates. Is thought to mediate docking of the importin/substrate complex to the nuclear pore complex (NPC) through binding to nucleoporin and the complex is subsequently translocated through the pore by an energy requiring, Ran-dependent mechanism. At the nucleoplasmic side of the NPC, Ran binds to the importin, the importin/substrate complex dissociates and importin is re-exported from the nucleus to the cytoplasm where GTP hydrolysis releases Ran. The directionality of nuclear import is thought to be conferred by an asymmetric distribution of the GTP- and GDP-bound forms of Ran between the cytoplasm and nucleus (By similarity).
Synonyms: IPO3; KPNB2B; FLJ12155; TRN2; IDDHISD
Tractability: PROTAC: ubiquitination databases record sites on it; its protein half-life has been measured.
Gene: Protein-coding gene on chromosome 19 (12,699,201 to 12,724,011, reverse strand). Ensembl gene ENSG00000105576.
Subcellular location: Cytoplasm; Nucleus
Subcellular location (Human Protein Atlas): Nucleoli; Nucleoplasm
Gene Ontology:
Molecular function: protein binding; nuclear import signal receptor activity; nucleocytoplasmic carrier activity; small GTPase binding
Biological process: intracellular protein transport; protein import into nucleus
Cellular component: cytoplasm; nucleus
Genetic constraint (gnomAD): Loss-of-function variants: 16 observed, 106.14 expected, observed/expected ratio (o/e) 0.15, 90% interval 0.1 to 0.23. The upper end of that interval is the gene's LOEUF score, 0.23, which puts it in group 1 of 6, group 1 being the genes least tolerant of losing a copy. Missense variants: 530 observed, 1,164 expected, observed/expected ratio (o/e) 0.46, 90% interval 0.42 to 0.49. Synonymous variants: 481 observed, 481.05 expected, observed/expected ratio (o/e) 1, 90% interval 0.93 to 1.08.
Homologues: Orthologues: chimpanzee TNPO2 (100% identical), macaque TNPO2 (100% identical), dog TNPO2 (99% identical), mouse Tnpo2 (99% identical), rat Tnpo2 (99% identical), guinea pig TNPO2 (98% identical), tropical clawed frog tnpo2 (93% identical), pig TNPO2 (90% identical), rabbit TNPO2 (90% identical), zebrafish tnpo2a (89% identical), Drosophila melanogaster Tnpo (72% identical), Caenorhabditis elegans imb-2 (51% identical), and 2 more. Paralogues in human: TNPO1 (85% identical), IPO4 (20% identical), IPO5 (19% identical), RANBP6 (18% identical), KPNB1 (14% identical).
Diseases named in the same sentence as TNPO2 in open-access papers:
TNPO2 is named in the same sentence as 16 diseases in open-access papers, as found by Europe PMC text mining. Sharing a sentence is not in itself a finding about the gene and the disease. The quoted sentences say what the papers report.
gastric cancer (3 papers, 2019 to 2022). A primary or metastatic malignant neoplasm involving the stomach. "By investigating the underlying mechanism of DYNC1I1 and TNPO2 in gastric cancer, the molecular markers that help in predicting the prognosis of gastric cancer were screened." (PMID 31605449, 2019). "It was found that TNPO2 was downregulated in gastric cancer cells at both mRNA and protein expression levels after SP1 knockdown." (PMID 31605449, 2019). "We further found that TNPO2 knockdown promoted gastric cancer cell apoptosis, and enhanced the functional expression of caspases 3 and 9, and P21 in this study, which indicated that activated P21 does not inhibit the caspase activity." (PMID 31605449, 2019). "The expression level of TNPO2 in gastric cancer and adjacent tissues was predicted by using the GEPIA website." (PMID 31605449, 2019). "DYNC1I1 showed positive correlation with TNPO2 in gastric cancer with a correlation coefficient of 0.69 (P < 0.05)." (PMID 31605449, 2019). "Next, SP1 was knocked down in gastric cancer cells with the aim to detect altered TNPO2 mRNA and protein expression levels." (PMID 31605449, 2019). "First, to verify the accuracy of the expression profile chip results, the correlation between DYNC1I1 and TNPO2 in gastric cancer was predicted by using the Gene Expression Profiling Interactive Analysis (GEPIA) website." (PMID 31605449, 2019). "Silencing of TNPO2 inhibited DNA replication in gastric cancer cells." (PMID 31605449, 2019). "The results found that “DNA replication” was the primary pathway observed from both methods, indicating that TNPO2 might regulate the biological behavior of gastric cancer cells through this pathway." (PMID 31605449, 2019). "At the same time, TNPO2 promoted gastric cancer cell proliferation and inhibited apoptosis by a mechanism that might be depending on the functional expression of P21." (PMID 31605449, 2019). "TNPO2 promoted gastric cancer cell proliferation and inhibited apoptosis, and this effect might be achieved by downstream engagement of P21." (PMID 31605449, 2019). "TNPO2 promotes gastric cancer cell proliferation and inhibits apoptosis by upregulating P21." (PMID 31605449, 2019). "Similarly, the EdU results showed that overexpression of TNPO2 in gastric cancer cells increased DNA replication." (PMID 31605449, 2019). "Furthermore, the role of TNPO2 in gastric cancer cells was explored, revealing TNPO2 in the promotion of proliferation of gastric cancer cells, and inhibition of apoptosis." (PMID 31605449, 2019). "In addition, flow cytometry was performed to detect the changes in the levels of gastric cancer cell apoptosis after 48 hours of transient knockdown of TNPO2 in HGC‐27, SGC‐7901, and SNU‐216 cells." (PMID 31605449, 2019). "Furthermore, the correlation between DYNC1I1 and SP1, as well as TNPO2 and SP1 in gastric cancer was verified by the GEPIA website." (PMID 31605449, 2019). "Although no statistical significance was observed, the expression of TNPO2 in gastric cancer was higher than that found in normal tissues." (PMID 31605449, 2019). "Knockdown of TNPO2 reduced the ability of gastric cancer cells to proliferate and increased the inhibition of gastric cancer cell proliferation over time when compared with negative controls." (PMID 31605449, 2019). "In this study, we found that TNPO2 knockdown promoted apoptosis of gastric cancer cells, while this effect was not achieved by abnormal cellular distribution of HuR." (PMID 31605449, 2019). "Moreover, DYNC1I1 upregulation could also enhance its downstream TNPO2 expression through SP1 overexpression to promote the proliferation and invasion of gastric cancer cells." (PMID 35002514, 2022). "Hence, in this study, we initially found that the downregulation of TNPO2 mRNA expression was most significantly observed after silencing DYNC1I1 in gastric cancer cells by gene expression microarray analysis, which indicated that DYNC1I1 as a potential upstream signaling mediator of TNPO2." (PMID 31605449, 2019).
gastric cancer (continued). "The role of TNPO2 in gastric cancer has not been studied till date." (PMID 31605449, 2019). "However, the results showed that the HuR protein showed no significant concentration in the cytoplasm, suggesting that TNPO2 does not promote apoptosis through this mechanism in gastric cancer cells." (PMID 31605449, 2019).
developmental delays (2 papers, 2024 to 2025). "TNPO2 variants associate with human developmental delays, neurologic deficits, and dysmorphic features and alter TNPO2 activity in Drosophila." (PMID 39590469, 2024). "Goodman and coworkers reported that the alterations in the TNPO2 gene could also lead to developmental delays, neurological defects, and dysmorphic changes in humans and mice." (PMID 41373546, 2025).
epilepsy (2 papers, 2021 to 2024). A brain disorder characterized by episodes of abnormally increased neuronal discharge resulting in transient episodes of sensory or motor neurological dysfunction, or psychic dysfunction. "In 2021, Leo, a newborn boy, showed symptoms of microcephaly and seizures, leading to a diagnosis of developmental delay and epilepsy stemming from a rare TNPO2 single-nucleotide variant causing toxic gain of function." (PMID 39062600, 2024).
autoimmune disease (1 paper, 2025). A disorder resulting from loss of function or tissue destruction of an organ or multiple organs, arising from humoral or cellular immune responses of the individual to their own tissue constituents. "Moreover, all the suggested genomic regions have been correlated with psoriasis and other autoimmune diseases except for one gene (TNPO2) and one non-coding region." (PMID 40725409, 2025).
colon cancers (1 paper, 2021). "Furthermore, with the exception of TNPO2 in lung cancer, OBSCN in liver cancer, and SEC16 in gastric and colon cancers, the high expression levels of the hub genes predicted a worse prognosis of the patients." (PMID 34359748, 2021).
tumor (5 papers, 2017 to 2024). "The prioritization of the hub genes in the gene expression profiles suggestive of tumor immune evasion and immunotherapy response occurs in the order of RAB31 > TNPO2 > OBSCN > IRAK3 > LIN9 > SEC16B." (PMID 34359748, 2021). "For the enhancer in chromosome 19, the target genes are TRMT1, TNPO2, NFIX, DNASE2, PRDX2, NANOS3, and LYL1, which was detected in 22 unique tumor samples." (PMID 29207666, 2017). "Other genes, TNPO2 and WDR83, were related to tumor development." (PMID 34645387, 2021). "Notably, RAB31, IRAK3, OBSCN, LIN9, TNPO2, and SEC16B expressions were inversely correlated with the gene expression profiles suggestive of tumor purity of the hub cancer." (PMID 34359748, 2021).
cancer (4 papers, 2009 to 2025). A tumor composed of atypical neoplastic, often pleomorphic cells that invade other tissues. "The high expression levels of RAB31, IRAK3, and TNPO2 were strongly correlated with gene expression profiles suggestive of dysfunctional T cell phenotypes in the six cancers." (PMID 34359748, 2021). "The possible association existing between ZNF83, TNPO2, ZFYVE1 and cancer was discussed in the present study for the first time." (PMID 19171046, 2009). "Specifically, single nucleotide variation (SNV) of OBSCN is the most frequently predicted gene alteration, while SNV of SEC16B, IRAK3, TNPO2, LIN9, and RAB31 constituted 9%, 5%, 5%, 4%, and 2% of genetic alterations in the TCGA cohort of the hub cancers." (PMID 34359748, 2021). "Similarly, the expression levels of RAB31, IRAK3, and SEC16B were inversely correlated, while TNPO2 and LIN9 were positively correlated with gene expression profiles suggestive of MDSCs infiltration in the six cancer types." (PMID 34359748, 2021).
neurodevelopmental disorder (2 papers, 2022 to 2023). A behavioral and cognitive disorder with onset during the developmental period that involves impaired or aberrant development of intellectual, motor, or social functions. "The last case was affected by two de novo diseases: a recurrent microdeletion and an additional dominant TNPO2-neurodevelopmental disorder; interestingly, only 15 other patients carrying de novo pathogenic variants in TNPO2 have been reported to date." (PMID 35886058, 2022).
TNPO2 also shares sentences with these, for which no sentence is quoted: colorectal cancer (1 paper); HIV-1 infection (1); liver cancer (1); lung carcinoma (1); malignant pleural mesothelioma (1); prostate carcinoma (1); psoriasis (1); Stomach Cancers (1).